BDNF (brain derived neurotrophic factor)
Diseases named in the same sentence as BDNF in open-access papers (continued):
Sharing a sentence is not in itself a finding about the gene and the disease.
depression (continued). "The increase in BDNF promotes neuroplasticity, neuron growth and differentiation, so it can effectively relieve anxiety and depression." (PMID 35323380, 2022). "Our previous research has also shown that alcohol exposure affected the depression-like behaviors of mice by altering the expression of BDNF." (PMID 35334870, 2022). "Clinical trials have pointed out that patients with major depressive disorders have low levels of BDNF in their blood, which is considered one of the major neurotrophic factors, important for the synaptic plasticity." (PMID 36295524, 2022). "In general, inhibition of FXR and activation of TGR5 in the hippocampus induces BDNF levels and mitigates depression-like symptoms in mice." (PMID 36339629, 2022). "Multiple studies have shown that changes in BDNF and proBDNF signaling pathways are present in the development of psychiatric disorders, such as depression, insomnia, and cognitive impairment." (PMID 36499215, 2022). "Since brain derived neurotrophic factor (BDNF), a neurotrophin that plays an important role in cognition and depression is also known to regulate Aβ production and deposition, we also examined the correlations between plasma BDNF and Aβ at Baseline." (PMID 35902554, 2022). "A jasmine tea intervention significantly attenuated CUMS-induced depression-like behavior in rats by upregulating BDNF and 5-HT expression in the hippocampus and cerebral cortex." (PMID 36499295, 2022). "The complex interaction between ECT and ketamine needs further investigation to decipher the role of BDNF signalling pathways in antidepressant therapies and their combination for patients with difficult-to-treat depression." (PMID 35203890, 2022). "It is important to mention that depression is accompanied not only by BDNF dysfunction and “depression‐like” symptoms but also by proinflammatory cytokines." (PMID 35848938, 2022). "BDNF, a critical neurotrophin in the etiology of depression and essential signaling molecule in nervous system development, is responsible for brain neuronal survival, synapse formation, and synaptic plasticity." (PMID 36614066, 2022). "Several studies have demonstrated that patients with depression have lower BDNF levels than healthy individuals." (PMID 36499295, 2022). "BDNF plays diverse roles in the pathogenesis of depression, depending on the brain region and the individual circuits." (PMID 36499295, 2022). "Here we review the role of BDNF in the hypothalamus and discuss important future research avenues to understand the implications of BDNF signaling in the hypothalamus for depression." (PMID 36466807, 2022). "The role of altered BDNF gene methylation in major depression has also been recently reviewed, and the data found consistent." (PMID 34989854, 2022). "Overall, the current study only performed RNA sequencing studies on a CUMS-based depression-like mouse model, BDNF knockdown mice (simulating depression-like), and IDO knock-out mice (antagonizing depression-like)." (PMID 35711916, 2022). "❑CPM.Primary Outcomes:◆FM patients: lower CPM, and inversely related to BDNF (controlling anxiety, depression, and pain catastrophizing)." (PMID 35579545, 2022). "BDNF/TrkB signaling is involved in various psychiatric diseases and is widely studied in the context of depression, anxiety disorders, schizophrenia, autism, and addiction." (PMID 36158555, 2022). "Our results show that MYR administration alleviated depression- and anxiety-like behaviors by regulating the BDNF-ERK signaling pathway." (PMID 35722162, 2022). "Treatment with both antidepressants and levothyroxine leads to a decrease in the level of pro-inflammatory cytokines, an increase in the level of BDNF, correlating with an improvement in clinical parameters of depression." (PMID 35455388, 2022). "Genetic factors also play a major role in depression, such as increased steroid hormones leading to suppression of BDNF and microRNA-132 gene affecting neuroplasticity." (PMID 35911274, 2022).
depression (continued). "BDNF is closely related to depression, so the research on depression and BDNF has been a research hotspot in recent years." (PMID 36291673, 2022). "In a model of LPS-induced depression, quercetin mitigates depressive behavior by modulating levels of BDNF and its related factors." (PMID 35630774, 2022). "Consistently, insufficient expression of BDNF and impairment of the BDNF-TrkB signaling axis are frequently observed in AD, PD and even chronic stress-induced depression." (PMID 35571135, 2022). "In the chronic unpredictable stress-induced depression rat model, miR-10b downregulation and BDNF upregulation have been shown in the hippocampus." (PMID 35916975, 2022). "Numerous studies have investigated the effect of antidepressants on the BDNF level of patients with depression." (PMID 35501732, 2022). "In the year 2010, Schmidt and colleagues investigated the potential functional significance of serum BDNF in various behaviour despair models of male C57Bl/6 mice to assess their depression- and anxiety-like behaviour." (PMID 36499240, 2022). "Low concentrations of brain derived neurotrophic factor (BDNF) have been recognized as facilitating neurogenesis and hippocampal atrophy in depression." (PMID 35215425, 2022). "In patients with perimenopausal syndrome, the serum BDNF level was much lower in depression group than that in non-depression group, and such level was negatively correlated with self-rating depression scale scores in the PD group." (PMID 35875795, 2022). "It is emphasized that BDNF works by facilitating the network’s activity in depression-like or antidepression-like manners." (PMID 36430254, 2022). "Changes in the BDNF level in the serum of patients with depressive disorders mean that BDNF can be considered as a biomarker of this disease." (PMID 35888708, 2022). "The level of brain-derived neurotrophic factor (BDNF), a neurotrophic protein, remarkably decreases in patients with MDD, which is considered as a risk factor for depression." (PMID 35664490, 2022). "Another double-blind, randomized and controlled clinical trial of 60 women with depressive disorder found that supplement with flaxseed oil twice a day for 10 weeks increased the concentration of serum BDNF and attenuated depressive symptoms." (PMID 36358502, 2022). "Supplementation with omega-3 FA increased serum BDNF levels and improved depressive symptoms in a randomized controlled trial with children and adolescents with depressive disorder." (PMID 36430921, 2022). "The central role of BDNF in depressive disorders and stress outcomes is well-established in the literature; however, BDNF exerts dynamic outcomes depending on the brain region or in this case cell type examined." (PMID 35722560, 2022). "Despite the numerous studies that investigate the role of BDNF on the dopaminergic mesolimbic pathway in depressive disorder and stress outcome, this is the first study to investigate the role of BDNF-TrkB signaling in specific NAc-MSN subtypes." (PMID 35722560, 2022). "According to a reported review, patients with significant depressive disorders had abnormally low serum BDNF levels, which increased after antidepressant treatment." (PMID 36506019, 2022). "Decreased brain-derived neurotrophic factor (BDNF) expression is well-known to play a critical role in the pathogenesis of depression." (PMID 33673283, 2021). "Taken together, it is important to study the relationship between the Nrf2 and BDNF in rodents with depression-like behaviors." (PMID 33627628, 2021). "In our study, TLE patients that showed history of depression also showed lower levels of methylation in BDNF or SLC6A4 genes." (PMID 34912196, 2021). "In summary, the present study identifies a critical role in mTORC1-Pdcd4 axis mediating BDNF mRNA translation in the hippocampus for the impairment of neuronal plasticity and depression-like behaviors in mice in response to chronic stress." (PMID 32203159, 2021).
depression (continued). "NRSF has multiple target genes including corticotrophin releasing hormone (CRH), brain-derived neurotrophic factor (BDNF), and serotonin receptor 1A, suggesting that it is involved in the pathophysiology of depression." (PMID 33804468, 2021). "Since the levels of BDNF in the brain in patients suffering from depression are impossible to measure, the determination of the level of BDNF in the blood is possible." (PMID 33673282, 2021). "Increasing BDNF/TrkB signaling activates the mechanistic target of rapamycin complex 1 (mTORC1), which decreases depression in the brain." (PMID 34743729, 2021). "UCMS induced anhedonia and hopeless behavior in mice, and changed expression levels of the depression-related genes BDNF, CREB, GR, SGK1, FKBP5, IL-1β, IL-6, and TNF-α in the frontal cortex and hippocampus." (PMID 34358084, 2021). "Perception strengthens by the correlations between emotional well-being, emotional rule, and depression symptoms scores with serum BDNF." (PMID 34769814, 2021). "Because BDNF concentration in the blood of patients with major depressive disorder is lower than that of healthy subjects under certain conditions, BDNF is expected to be a candidate for a biomarker for a diagnosis of depression." (PMID 33924992, 2021). "Potential mechanisms of depression involving herbal medicines and their specific compounds include elevated 5‐HT level and downstream BDNF pathway." (PMID 33598202, 2021). "The transcription factor erythroid 2-related factor 2 (Nrf2) and brain-derived neurotrophic factor (BDNF) play a key role in depression." (PMID 33627628, 2021). "Decreased levels of BDNF and BDNF receptor were also demonstrated in the hippocampus of patients with depression postmortem." (PMID 34064233, 2021). "TRPC6 is involved in the signaling of brain-derived neurotrophic factor (BDNF), which is a pathophysiologically relevant neuropeptide in depression and stress disorders." (PMID 34577594, 2021). "We next review the roles of BDNF in these regions, as well as the involvement of the dorsal striatum in depression pathogenesis, with a focus on stress sensitivity." (PMID 34577589, 2021). "Studies have shown that other neurotrophic factors, such as nerve growth factor (NGF) and BDNF, also play a key role in the neurophysiological mechanisms that relieve depression." (PMID 34040537, 2021). "In preclinical in vivo studies in rodents, a correlation between hippocampal BDNF and allopregnanolone levels is supported by studies that aimed to model depression using a variety of protocols." (PMID 33578758, 2021). "We further evaluated the expression of PI3K/Akt/mTOR-mediated BDNF/TrkB pathway-related proteins to investigate the role of SY in depression." (PMID 33584387, 2021). "As such, an increasing number of studies have investigated strategies to elevate circulating BDNF concentration as well as their potential to treat or prevent conditions related to neuronal impairments such as Alzheimer`s disease, depression and schizophrenia." (PMID 34882699, 2021). "Increases in BDNF serum levels were observed, as well as improvements in the Beck Depression Scale, the Insomnia Severity Score, and two out of three scales of the Maslach Burnout Inventory (MBI), i.e., depersonalization and emotional exhaustion." (PMID 34640441, 2021). "One further mechanism of depression is a deficit of neurotrophic factors, such as brain-derived neurotrophic factor (BDNF), which leads to altered synaptic plasticity and then to neuronal dysfunction and cell death." (PMID 34055858, 2021). "There are few randomized controlled studies on the impact of rTMS on BDNF in patients with depression." (PMID 34207545, 2021). "Prenatal stress exposure was reported to increase HDAC expression and decrease BDNF expression in the hippocampus, resulting in anxiety- and depression-like behaviors." (PMID 34065586, 2021).
depression (continued). "To elucidate the molecular pathways in the neuroplasticity-related mechanisms, we first assessed the components of BDNF signalling and their involvement in the pathophysiology of depression." (PMID 34876186, 2021). "Lower BDNF levels on day one post-stroke were correlated with a higher incidence of post-stroke depression (OR = 0.551, 95%CI: 0.389–0.779, p = 0.001), with a cut-off value of BDNF < 5.86 ng/mL to be predictive of depression development in the first two weeks." (PMID 33809965, 2021). "The interaction of exercise with depression is complex with apparent contributions of multiple genes in the BDNF and MAP kinase pathways." (PMID 33589676, 2021). "Up-regulation of this factor occurs in the amygdala and nucleus accumbens of persons with depression whereas down-regulation of BDNF occurs in the prefrontal cortex and hippocampus." (PMID 33673282, 2021). "Research has shown that brain-derived neurotrophic factor (BDNF) plays an increasingly important role in anxiety and depression." (PMID 34040537, 2021). "We also highlighted BDNF function in the dorsal striatum as a novel role in depression as a regulator of stress sensitivity." (PMID 34577589, 2021). "Decreased BDNF levels and reduced numbers and density of dendritic spines were observed in a mouse model of depression exposed to RSDS." (PMID 34577589, 2021). "Although some studies have shown lower levels of blood BDNF in patients with major depression (MD) in comparison with those of healthy subjects, the results are inconsistent." (PMID 34421705, 2021). "BDNF in serum or plasma is increasingly used as a putative biomarker for depression, and some studies revealed that lower levels of BDNF in the blood of depressed patients are improved after long-term treatment of certain antidepressants." (PMID 34776888, 2021). "Masi and Brovedani demonstrated that neurotrophic factors such as BDNF play a major role in the development of depression." (PMID 34046326, 2021). "In conclusion, this review discussed the relationship between BDNF and PSD in detail, suggesting that the changes in serum BDNF concentration can be associated with depression after stroke insults." (PMID 34141514, 2021). "It has been extensively shown that continuous exposure to stress decreases the level of hippocampal BDNF in animal models of depression, and BDNF expression has been found to be decreased in the brains of patients with major depressive disorders." (PMID 34658847, 2021). "In particular, a prominent hypothetical model for depression involves the epigenetic mechanism of histone methylation that transduces environmental stress into decreased BDNF expression." (PMID 34225758, 2021). "Another study demonstrates that healthy individuals with a family history of depression exhibited higher peripheral BDNF levels, presumably suggesting hypomethylation in those individuals with higher familial risk." (PMID 34970165, 2021). "Together, we have demonstrated for the first time that d-serine protects against depression by inhibiting BDNF signaling pathway and regulating synaptic adaptations in NAc." (PMID 34654365, 2021). "All these demonstrated the interaction between the BDNF-mTORC1 pathway and the monoaminergic system in the occurrence and treatment of depression." (PMID 33628219, 2021). "Concluding, we observed a significant association between lower levels of methylation the BDNF and SLC6A4 gene promoters and presence of MDD or life history of depression in patients with TLE." (PMID 34912196, 2021). "In depression, neuroplasticity, which is mediated by regulatory proteins, such as BDNF, is disrupted." (PMID 33723349, 2021). "Conversely, bilateral infusion of BDNF into the hippocampal dentate gyrus has been shown to produce antidepressant-like effects in behavioral models of depression." (PMID 34924969, 2021). "Our present study using ELISA analysis verified that BDNF expression was inhibited in the mPFC and hippocampus in LPS-induced depression in mice." (PMID 34207497, 2021).
depression (continued). "In conclusion, our results indicated that Rb1 exerts promising antidepressant-like effects in mice with CSDS-induced depression, and its effects were facilitated by enhancing the BDNF signaling cascade and upregulation of hippocampal neurogenesis." (PMID 34658847, 2021). "Epigenetic regulation of BDNF in depression has been increasingly studied, particularly DNA methylation." (PMID 34325733, 2021). "Luteolin treatment also significantly increased mature BDNF, dopamine, and noradrenaline levels in the hypothalamus of LPS-induced depression mice." (PMID 34790666, 2021). "In animal models of depression and schizophrenia, BDNF levels were found to be abnormally regulated." (PMID 34398437, 2021). "A loss of serotonergic neurons was observed in a mouse model of depression due to reduced BDNF in the hippocampus, since these neurons grow and survive via BDNF-TrkB signaling cascades." (PMID 34577589, 2021). "The extracellular-regulated kinase (ERK)–cyclic AMP-response element-binding protein (CREB)–brain-derived neurotrophic factor (BDNF) signaling pathway is an important factor in the pathogenesis of depression." (PMID 34439529, 2021). "In vitro study showed that miR-132 and miR-182 reduced the expression of brain-derived neurotrophic factor (BDNF), which was greatly important in the aetiology of depression." (PMID 34947970, 2021). "More specifically, this therapeutic research has been proved to prevent synaptic lesion and BDNF expression abnormalities in CRS-induced depression model." (PMID 34772918, 2021). "A large number of studies have shown that vagus nerve stimulation (VNS) improves the symptoms of several diseases including ischemic stroke, Parkinson's disease, and depression, possibly in conjunction with the upregulated expression of BDNF." (PMID 34526917, 2021). "After a 4-week treatment program with EOs, the level of anxiety and depression of the subjects decreased, while the plasma BDNF level (reflecting the brain tissue level of BDNF) significantly increased." (PMID 34063646, 2021). "We used Nrf2 KO mice with a depression-like phenotype to confirm the role of Nrf2 and BDNF crosstalk in the pathogenesis of depression." (PMID 33627628, 2021). "One study found that aerobic exercise can increase the levels of brain-derived neurotrophic factor, which has been shown to decrease in individuals with severe depression." (PMID 34690713, 2021). "Our previous study also emphasized the critical translational mechanism of BDNF in depression, and found Pdcd4 is the key regulator in that." (PMID 34772918, 2021). "Patients with a history of mild to moderate TBI and a diagnosed depression responded differently to Citalopram, depending on BDNF rs6265, where the best responders were val-homozygotes." (PMID 33808272, 2021). "Inflammation from stroke and depression has been shown to impact neuroplasticity, as evidenced by the decreased availability of brain-derived neurotrophic factor (BDNF) in synapses." (PMID 33919670, 2021). "The KBD formula normalized UMCS-induced anhedonia and hopeless behaviors in mice by restoring expression of the depression-related genes BDNF, CREB, GR, SGK1, FKBP5, IL-1β, IL-6, and TNF-α in the frontal cortex and hippocampus brain regions." (PMID 34358084, 2021). "BDNF levels have been reported to be decreased in the brains of patients with major depressive disorder, bipolar disorder, schizophrenia, Alzheimer’s disease, and Parkinson’s disease." (PMID 34977362, 2021). "In an animal model of depression using the forced swimming test, rats exposed to this chronic stressor showed significant decreases in the plasma levels of both BDNF and motilin, which occurred in parallel with increases in CRH and cortisol." (PMID 34575041, 2021). "BDNF has been extensively studied in the context of depression and animal models of stress, as well as in other brain disorders such as schizophrenia." (PMID 34225758, 2021).